PIGR (polymeric immunoglobulin receptor)
Diseases named in the same sentence as PIGR in open-access papers (continued):
Sharing a sentence is not in itself a finding about the gene and the disease.
tumor (continued). "The mechanistic basis for the putative tumour suppressing properties of pIgR in these cancers merits further study." (PMID 25397670, 2014). "Increased expression of polymeric immunoglobulin receptor (pIgR) in tumor tissue has been detected in various types of cancer." (PMID 24699841, 2014). "There was a non-significant trend towards an improved OS for cases with high tumour-specific PIGR expression (p = 0.054)." (PMID 24694107, 2014). "Kaplan-Meier analysis of the entire cohort (n = 153) demonstrated a significantly prolonged OS (p = 0.013) and OCSS (p = 0.009) for patients with tumours displaying high PIGR expression." (PMID 24568264, 2014). "The lowest expression of pIgR was seen in tumours of pancreatic origin, i.e. pancreatobiliary type and the highest in primary tumours of duodenal origin, i.e. intestinal type, which is in line with the more favourable prognosis in the latter." (PMID 25397670, 2014). "PIGR expression was significantly higher in fallopian tubes compared to primary tumours and metastases (p < 0.001) and lower in carcinoma of the serous subtype compared to other carcinomas (p < 0.001)." (PMID 24568264, 2014). "Another plausible explanation for the favourable prognosis in patients with tumours displaying high expression of PIGR has been suggested." (PMID 24568264, 2014). "High pIgR expression has been reported to correlate with a less aggressive tumour phenotype and an improved prognosis in several human cancer types." (PMID 25397670, 2014). "Given its important immunoregulatory function, the interplay between pIgR and the inflammatory microenvironment of tumours warrants further study." (PMID 25397670, 2014). "The results demonstrate a significantly higher PIGR expression in fallopian tubes compared to primary and secondary tumour sites." (PMID 24568264, 2014). "PIGR expression was significantly higher in fallopian tubes compared to primary tumours (p = 0.0009) and to metastases (p = 0.0004)." (PMID 24568264, 2014). "Kaplan-Meier analysis revealed a significantly improved OS (p = 0.013) and OCSS (p = 0.009) for patients with tumours displaying high expression of PIGR." (PMID 24568264, 2014). "Five-year overall and recurrence free survival according to continuous pIgR expression in the entire cohort, intestinal and pancreatobiliary type tumours." (PMID 25397670, 2014). "In two of these cases, PIGR mRNA expression levels were successfully evaluated in formalin-fixed paraffin-embedded tissue from paired primary tumours and lymph node metastases." (PMID 25397670, 2014). "pIgR expression was significantly down-regulated in lymph node metastases as compared with primary tumours (p = 0.018)." (PMID 25397670, 2014). "pIgR expression was significantly lower in lymph node metastases compared to primary tumours in the entire cohort (p = 0.018), and in pancreatobiliary type (p = 0.033) but not in intestinal type tumours." (PMID 25397670, 2014). "PIgR expression was significantly higher in benign pancreatic tissue compared to primary and metastatic tumours in the full cohort as well as in separate analysis of intestinal and pancreatobiliary type tumours (p<0.001 for all)." (PMID 25397670, 2014). "Kaplan-Meier analysis revealed a significantly reduced 5-year OS for patients with tumours displaying low pIgR expression (logrank p<0.001)." (PMID 25397670, 2014). "In order to validate the results obtained by 1D-SDS-PAGE, three proteins, GRP94, pIgR and IgGFcBP were chosen to determine their expression in tumour and healthy neighboring tissue." (PMID 22152070, 2011). "They indicate that PIGR might play an anti-tumor role by activating tumor immunity in BRCA tissues, thereby improving the prognosis of BRCA patients." (PMID 40386563, 2025). "Additionally, PIGR plays an anti-tumor role in ESCC tumor immunity in an antigen-specific manner during NY-ESO-1 vaccinations." (PMID 40386563, 2025). "In vivo experiments further revealed that overexpression of PIGR inhibits tumor growth." (PMID 40386563, 2025).
tumor (continued). "Nevertheless, PIGR has been shown to play an anti-tumor role in several other human malignancies." (PMID 40386563, 2025). "PIGR correlates with tumor immunity and exerts anti-tumor effects in BRCA." (PMID 40386563, 2025). "Moreover, among the human prostate luminal epithelial cell–type classifiers described previously, fNICD2-#1 luminal tumor foci expressed all 4 markers of luminal-C cells (TASCSTD2/PIGR/PSCA/KRT4)." (PMID 39024561, 2024). "PIGR has been reported to promote tumor growth and participate in immune disorders." (PMID 37365497, 2023). "We further constructed gene modules in AT2 (LUAD) and basal (LUSC) cells, which revealed that many tumor-related genes in cells from stage-I patients, including PIGR, AZGP1, BTG2, EGR1, and LMO3 in AT2 cells from LUAD, and AQP3, SPHK1, PPT1, and PDIA6 were found in basal cells from LUSC." (PMID 35027529, 2022). "PIGR was positive with tumor-infiltrating of B cells, Th17 cells, T cells, and Th2 cells." (PMID 36157233, 2022). "Together, PIGR may serve as a powerful prognostic biomarker and putative tumor suppressor by suppressing the AKT-FOXO3/4 axis by downregulating LAMB3 in CRC." (PMID 35992840, 2022). "Furthermore, we analyzed the relationship between PIGR and tumor-infiltrating immune cells (TIICs) in CRC." (PMID 36157233, 2022). "Additionally, polymeric immunoglobulin receptor (pIgR) was recently reported to promote cell transformation and proliferation, contributing to tumour growth." (PMID 35090441, 2022). "Finally, IgA co-immunoprecipitated with the secretory component in OVCAR3 supernatants, and this was again abolished by transcytosis inhibitors or PIGR ablation in tumour cells." (PMID 33536615, 2021). "Given the involvement of many of these genes (such as C3, CD74, HLA-DR, STRA6, IGFBP4 and PIGR) in immune-mediated processes, it is tempting to speculate that their up-regulation indicates immune-mediated tumour control that is lost in malignant tumours." (PMID 32218455, 2020). "Strikingly, for genes in cluster ii), which are specifically up-regulated in AAS, high expression of 7 of the top 10 genes (C3, CD74, HLA-DRA, STRA6, IGFBP4, PIGR, and TNIP1) was strongly associated with better cumulative survival than tumours with low expression of these genes." (PMID 32218455, 2020). "Furthermore, we aimed to investigate if these markers correlate with expression of the polymeric immunoglobulin receptor (PIGR), which has previously been described as an indicator of a less aggressive tumour phenotype and improved survival in EOC." (PMID 27048364, 2016). "Furthermore, CD20 expression was revealed to have an inverse relationship with tumour-specific expression of PIGR, a receptor that binds polymeric immunoglobulin molecules at the surface of epithelial cells." (PMID 27048364, 2016). "pIgR expression could be evaluated in 172/175 (98.3%) primary tumours and in 96/105 (91.4%) lymph node metastases." (PMID 25397670, 2014). "Moreover, patients with high tumour-specific expression of PIGR had a significantly prolonged survival in unadjusted analysis, but not when adjusted for age, grade and clinical stage." (PMID 24568264, 2014). "After an initial screening in the Human Protein Atlas portal, a validated antibody was selected for extended analysis of immunohistochemical PIGR expression in tissue microarrays with tumours from 154 incident cases of EOC from two pooled prospective population-based cohorts." (PMID 24568264, 2014). "However, as this study only included six patients with samples from all three locations, further studies are needed to analyse PIGR expression related to individual tumour progression." (PMID 24568264, 2014). "PIGR expression could be evaluated in 173/175 (98,9%) of the primary tumours and in 75/81 (92.6%) of the sampled lymph node metastases." (PMID 24694107, 2014).
tumor (continued). "Notably, recent studies in a large cohort of patients with ovarian cancer revealed that polyclonal IgA antibodies derived from TABs bind to IgA receptors on tumor cells, triggering pIgR-mediated IgA transcytosis and impeding tumor growth, ultimately enhancing tumor cell killing by T cells." (PMID 39026670, 2024). "Notably, B cells and PCs preferentially express immunoglobulin A (IgA), which can be internalized by tumor cells via binding to the polymeric immunoglobulin receptor (PIGR) in an antigen-independent manner, rendering tumor cells more susceptible to T cell-mediated cytotoxicity." (PMID 39026670, 2024). "Therefore, we assumed that PIGR might play a tumor suppressor role in CRC by affecting cell adhesion and altering extracellular matrix components." (PMID 35992840, 2022). "Moreover, the significant down-regulation of pIgR in lymph node metastases compared to primary tumours in the entire cohort, was more evident in pancreatobiliary type tumours than in intestinal type tumours, which supports a tumour suppressive role for pIgR in this type of tumours as well." (PMID 25397670, 2014). "The polymeric immunoglobulin receptor (PIGR) has been proposed to be a candidate prognostic biomarker in a few cancer forms, and one previous study reported that reduced PIGR expression signifies more aggressive tumours of the distal esophagus and gastroesophageal junction (GEJ)." (PMID 24694107, 2014). "Mechanistically, FCGBP modulated the PIGR/JAK2/STAT3 signaling pathway, thereby exerting both anti-tumor and anti-CDDP resistance effects." (PMID 41560312, 2026). "In hepatocellular carcinoma, IgM facilitates tumor metastasis through epithelial-mesenchymal transition (EMT), mediated by the polyimmunoglobulin receptor (pIgR)." (PMID 41357192, 2025). "This included PIGR in the subclone mapping to P5.1 and PTGS1 in the subclone mapping to P5.2, thus, we henceforth refer to these tumour subclones as PIGR+ tumour cells and PTGS1+ tumour cells, respectively." (PMID 38570491, 2024). "We first used neighbourhood analyses to survey the proportions of each cell type in the local neighbourhood of PIGR+ and PTGS1+ tumour cells." (PMID 38570491, 2024). "To examine the association of the subclones with other cell types, we removed all homotypic interactions between tumour cells and recalculated the proportions of heterotypic interactions involving the PTGS1+ and PIGR+ subclones and other cells." (PMID 38570491, 2024). "A recent study in EC has demonstrated that polymeric immunoglobulin receptor (pIgR) dependent, antigen-independent IgA occupancy triggers the activation of interferon (IFN) and tumor necrosis factor (TNF) signaling pathway in tumor cells." (PMID 37584707, 2023). "Taken together, five tumor antigens (ALOX15B, HS3ST2, PIGR, ZMYND15, and LIMK1), with potentially provocative effects on immunological functions, were identified and considered as eligible candidates for anti-PRCC mRNA vaccine development." (PMID 36836593, 2023). "After that, five tumor antigens (ALOX15B, HS3ST2, PIGR, ZMYND15, and LIMK1) were identified to be candidates for the mRNA-based vaccine development, all of which were correlated with survival time of PRCC patients and the degree of APC infiltration." (PMID 36836593, 2023). "Five tumor antigens, including ALOX15B, HS3ST2, PIGR, ZMYND15 and LIMK1, were identified for PRCC, which were correlated with patients’ prognoses and infiltration levels of APCs." (PMID 36836593, 2023). "Exploration of the expression network indicated that inflammatory genes (CXCL8, CXCL3, PIGR, and RNASE1) and Wnt pathway genes (GAST, REG1A, TFF3, and ZG16B) are upregulated in tumor stem cells of UGICs." (PMID 35646860, 2022). "For instance, the expression of the ciliated epithelial markers, including FOXJ1, PIGR, CAPS, and GDF15, declined during the process of metastasis, although they were overexpressed in EC2 that mainly consisted of primary tumor cells." (PMID 34459128, 2021).
tumor (continued). "As a vital inflammatory mediator 7, PIGR played an important role in hepatitis B virus (HBV) infection, chronic liver inflammation, tumor growth, recurrence, and metastatic progression in HCC 10-12." (PMID 33390805, 2021). "Two genes, PIGR and BTNL9, showed downregulation by 32-fold and 26-fold, respectively, in tumor tissues compared to normal tissues." (PMID 31182966, 2019). "The epithelial cell cluster unique to patient HG3 from this tumor had eleven differentially expressed genes with highest expression found in SST, TFF3 and PIGR." (PMID 30383866, 2018). "However, since the number of cases available for analysis in each subgroup was rather small, future studies encompassing tumours from larger patient cohorts are warranted to determine whether the prognostic value of PIGR expression differs by anatomical location in these cancer forms." (PMID 24694107, 2014). "This study provides a first demonstration of PIGR expression in human fallopian tubes, primary EOC tumours and metastases." (PMID 24568264, 2014). "However, studies on colorectal and hepatocellular cancer suggest that SC serum levels are not necessarily associated with tumour-specific PIGR expression and the described association might therefore not be applicable for the present study." (PMID 24568264, 2014). "On the other hand, the pIgR was identified in the same band as GRP94, which showed a higher intensity in tumour tissue." (PMID 22152070, 2011). "Research has clarified that M1 macrophages raised PIGR levels in BRCA cells employing IL-1β, suggesting that targeting M1 macrophages to increase PIGR may be a potential anti-tumor strategy." (PMID 41450825, 2025). "The qRT-PCR results showed that CXCL1, PIGR, and TNFRSF14 were significantly lower expressed in BC tissues than adjacent tissue, while CXCL13 and NKAIN were significantly upregulated in BC tissues compared with adjacent tumor tissue." (PMID 39287311, 2024). "CAFs-Exo was found to be involved in tumor immune regulation through hsa-miR-139-5p, ACTR2 and EIF6, while PIGR, CD81, UACA and PTTG1IP may be potentially effective targets for the treatment of OSCC in the future." (PMID 37365497, 2023). "Given the limited sample set, the expression of PIGR showed no marked contrast between BC and its corresponding non-tumor tissues." (PMID 38162504, 2023). "PIGR mRNA was significantly upregulated in tumor tissues compared to nontumor tissues in Guichard Liver, Guichard Liver 2 and TCGA Liver from Oncomine database (all p < 0.0001), as well as in GSE55092 and GSE60502 profiles in GEO databases (both p < 0.05)." (PMID 33390805, 2021). "In further support of the relevance of antigen recognition, significant anti-tumour effects were elicited by clonally expanded IgA, but not by control irrelevant IgA against PIGR-ablated autologous tumours." (PMID 33536615, 2021). "Furthermore, a list of genes, including AZGP1, KRT19, and PIGR, was identified as differentially expressed between TNBC and other tumor types, suggesting their potential use as discriminatory markers." (PMID 31134153, 2019). "A total number of 25 (14.5%) primary tumours and 20 (20.8%) metastases were completely negative for pIgR expression, and in the other cases, pIgR was expressed in varying fractions and intensities." (PMID 25397670, 2014). "A total number of 47/173 (27.2%) of primary tumours and 32/75 (42.7%) of lymph node metastases were negative for PIGR expression." (PMID 24694107, 2014). "There was a tendency towards a lower PIGR expression in lymph node metastases as compared to primary tumours, although these results were not significant." (PMID 24694107, 2014). "There was, however, no obvious heterogeneity in PIGR expression between duplicate tissue cores, and of note duplicate cores were obtained from different blocks of the primary tumour and different lymph node metastases in cases with more than one metastasis." (PMID 24694107, 2014).
tumor (continued). "PIGR expression did not remain an independent prognostic factor in subgroup analysis according to tumour location (data not shown)." (PMID 24694107, 2014). "As samples from all three locations were only available for six patients, this study did not allow for a meaningful analysis of PIGR expression related to individual tumour progression." (PMID 24568264, 2014). "We found that PIGR, LPRP, PLUNC, and EMP1 are downregulated in almost all the tumours." (PMID 14612907, 2003). "However, multivariate Cox regression showed that PIGR was not an independent prognostic marker potentially because PIGR exhibits strong collinearity with tumor stage in the multivariate regression model." (PMID 35992840, 2022). "Meanwhile, PIGR had a negative correlation with tumor-infiltrating NK cells and Tcm cells." (PMID 36157233, 2022). "Consequently, IgA and pIgR colocalized at tumour beds within cytokeratin (PCK)-positive tumour islets in 273 HGSOCs we analysed, and IgA–pIgR colocalization—but not pIgR-overexpression alone or stromal IgA—is associated with improved survival." (PMID 33536615, 2021). "A limitation to this study is the lack of information on residual tumour after surgery, however, as PIGR expression did not provide any independent prognostic value, inclusion of this information in the multivariable model is not likely to have altered our findings." (PMID 24568264, 2014). "pIgR expression could be evaluated in all 50 samples with non-malignant tissue, in 172/175 (98.3%) of the primary tumours and in 96/105 (89.5%) of the sampled lymph node metastases." (PMID 25397670, 2014). "Furthermore the lack of positive conversion of PIGR expression from the primary tumour to lymph node metastasis, suggests that analysis of PIGR in the primary tumour should be sufficient for prognostication purposes." (PMID 24694107, 2014). "It seems that the absence of pIgR in the tumour cells could induce a depletion of the immune response that promotes their malignant potential; nevertheless, its role in cancer development remains unknown." (PMID 22152070, 2011). "Interestingly, the importance of pIgR is not restricted to immunology, since changes in its expression, either increase or decrease, have been described in different types of tumours." (PMID 22152070, 2011). "To explore whether methylation of the PIGR promoter in CRC tissues was altered during CRC development, we first detected three CpG loci targeting the PIGR promoter region using targeting bisulfite sequencing in 279 CRC tumor tissues and 27 adjacent normal tissues in our cohort." (PMID 35992840, 2022). "Although EpCAM, PIGR, OLFM4, and CLDN4 have been previously identified as membrane markers for GC, they did not effectively discriminate between HM and tumor tissue in our patient cohort." (PMID 40868067, 2025). "The same result was observed in the expression pattern of polymeric immunoglobulin receptor (PIGR), which demonstrated a negative 32-fold change (12,789 RPKM in normal tissues and 412 RPKM in tumor tissues)." (PMID 31182966, 2019).